OR7C1 (olfactory receptor family 7 subfamily C member 1)
Description:
Odorant receptor.
Synonyms: OR7C4; OR19-5; CIT-HSP-146E8; HSTPCR86P; TPCR86
Tractability: Antibody: its Gene Ontology location is reachable by antibodies, with high confidence; UniProt places it where antibodies can reach, with medium confidence; UniProt predicts a signal peptide or a membrane-spanning region.
Gene: Protein-coding gene on chromosome 19 (14,789,260 to 14,835,376, reverse strand). Ensembl gene ENSG00000127530.
Subcellular location: Cell membrane
Pathways (Reactome):
Sensory Perception: Expression and translocation of olfactory receptors; Olfactory Signaling Pathway
Gene Ontology:
Molecular function: protein binding; G protein-coupled receptor activity; olfactory receptor activity
Biological process: signal transduction; spermatogenesis; detection of chemical stimulus involved in sensory perception of smell; G protein-coupled receptor signaling pathway
Cellular component: plasma membrane; membrane
Genetic constraint (gnomAD): Missense variants: 246 observed, 303.75 expected, observed/expected ratio (o/e) 0.81, 90% interval 0.73 to 0.9. Synonymous variants: 123 observed, 128.66 expected, observed/expected ratio (o/e) 0.96, 90% interval 0.82 to 1.11.
Homologues: Orthologues: chimpanzee OR7C1 (98% identical), macaque OR7C1 (91% identical), dog OR7C1 (78% identical). Paralogues in human: OR7C2 (78% identical), OR7A5 (66% identical), OR7A10 (66% identical), OR7A17 (65% identical), OR7D4 (64% identical), OR7D2 (63% identical), OR7G3 (62% identical), OR7E24 (60% identical), OR7G2 (59% identical), OR7G1 (58% identical), OR1N1 (55% identical), OR1G1 (54% identical), and 116 more.
Diseases named in the same sentence as OR7C1 in open-access papers:
OR7C1 is named in the same sentence as 7 diseases in open-access papers, as found by Europe PMC text mining. Sharing a sentence is not in itself a finding about the gene and the disease. The quoted sentences say what the papers report.
colon cancer (5 papers, 2018 to 2021). "For example, OR7C1 was reported to have essential roles in the maintenance of colon cancer initiating cells." (PMID 34204736, 2021). "Olfactory Receptors (OR) are reported to have different expression levels in tissue of various origin, and OR7C1 represents a prognostic biomarker in colon cancer." (PMID 32817744, 2020). "OR7C1 (olfactory receptor family 7 subfamily C member 1) represented a novel marker of colon cancer-infiltrating cells (CICs)." (PMID 33043022, 2020). "Another biomarker for colon cancer is OR7C1; its expression functions as a prognostic marker for colorectal cancer." (PMID 29497600, 2018). "In addition, it has been reported that OR7C1 mRNA is preferentially expressed in colon cancer cells than in normal colon cells; OR7C1 knockdown delayed tumor progression in several colorectal cancer cell lines." (PMID 34502185, 2021). "Another OR, OR7C1, was shown to be a marker for colon cancer-initiating cells and might be a potent immunotherapy target." (PMID 29497600, 2018). "Flow cytometry indicated that OR7C1-positive cells showed higher tumorigenicity than OR7C1-negative cells, suggesting that OR7C1 is a novel functional marker for colon cancer initiation." (PMID 34204736, 2021).
colorectal cancer (3 papers, 2018 to 2021). A primary or metastatic malignant neoplasm that affects the colon or rectum. "Furthermore, a high expression of OR7C1 correlated with poor prognosis in colorectal cancer patients." (PMID 34204736, 2021).
leukaemia (1 paper, 2020). "Currently, data of OR7A5 and OR7C1 in leukaemia are not reported." (PMID 32817744, 2020).
cancer (1 paper, 2019). A tumor composed of atypical neoplastic, often pleomorphic cells that invade other tissues. "Olfactory receptor family 7 subfamily C member 1 (OR7C1) was also found to be a novel marker for colon-cancer-initiating cells (CICs)." (PMID 31781505, 2019).
OR7C1 also shares sentences with these, for which no sentence is quoted: tumor (2 papers); colon (1); lung carcinoma (1).